BMP4 (bone morphogenetic protein 4)
Diseases named in the same sentence as BMP4 in open-access papers (continued):
Sharing a sentence is not in itself a finding about the gene and the disease.
breast carcinoma (continued). "When an inhibitory factor for BMP-4 was added to the co-cultures, migration of breast cancer cells was decreased and their CXCR-4 expression downregulated, demonstrating that BMP-4 acted as an activator of the CXCR-4/CXCL-12 pathway." (PMID 27571063, 2016). "Neutralization of BMP-4 in NDRG2-expressing breast cancer cells results in the rescue of MMP9 mRNA expression and migration capacity." (PMID 26506239, 2016). "NDRG2 also inhibits the metastatic potentials of breast cancer cells through inducing bone morphogenetic protein 4 and subsequent suppression of MMP-9 expression." (PMID 25889839, 2015). "Previous data from us and others showed that BMP4 is able to reduce the growth of breast cancer cells whilst inducing cell migration and invasion." (PMID 24053318, 2013). "Previous data from us and others clearly demonstrate that BMP4 reduces the proliferation of breast cancer cells in 2D culture, and similar results have been reported in other tumor types." (PMID 24053318, 2013). "Fibroblasts that were stimulated with BMP4 were found to enhance mammary carcinoma cell invasion, and these effects were inhibited by a BMP receptor kinase antagonist." (PMID 23840733, 2013). "We have previously shown that BMP4 reduces proliferation and increases migration of breast cancer cells in vitro." (PMID 24053318, 2013). "We were able to demonstrate that BMP4 stimulation of both mouse and human fibroblasts was sufficient to enhance mouse and human breast carcinoma invasion." (PMID 23840733, 2013). "Similar to breast cancer cell lines, BMP4 decreased the proliferation of the MCF-10A cells as determined by cell counting and alamarBlue." (PMID 24053318, 2013). "We have previously shown that BMP4 reduces breast cancer cell proliferation through G1 cell cycle arrest and simultaneously induces migration in a subset of these cell lines." (PMID 24053318, 2013). "Nevertheless, the majority of the data implies that BMP4 has a dualist effect on breast cancer cells, with inhibition of cell proliferation and induction of a migratory phenotype." (PMID 24053318, 2013). "Our analyses unveiled that treatment of breast cancer cells with either BMP4 or BMP7 resulted in the coordinated expression of a group of genes (clusters A and B, respectively)." (PMID 22118688, 2011). "For the most part, the data suggest promotion of these cellular abilities by BMP4 in several breast cancer cell lines and in normal breast epithelial cells, while a study in which only MDA-MB-231 cells were analyzed reported the opposite phenotype." (PMID 22118688, 2011). "BMP4 was shown to inhibit cell proliferation in a panel of breast cancer cell lines by inducing a G1 cell cycle arrest." (PMID 22118688, 2011). "Bone morphogenetic protein 4 stimulates outgrowth of normal mammary buds, is upregulated in human breast cancer, and was increased by 6.1 fold in the SRC1-/- tumor model." (PMID 21080969, 2010). "In a mouse xenograft model using breast cancer cells, BMP4 treatment led to an increase in the number of bone metastases, suggesting that BMP4 could have a potential role in promoting bone metastasis." (PMID 40593552, 2025). "Interestingly, a study by Eckhardt and colleagues showed that loss of BMP4 or its downstream effector, SMAD7, promotes breast cancer metastasis." (PMID 40001874, 2025). "Our findings indicate that therapeutic inhibition of cholesterol biosynthesis may be a viable approach to suppress breast cancer metastasis, possibly with greater benefit for patients with low-BMP4-expressing tumours as exemplified by the 231-HM tumour line." (PMID 39273106, 2024). "Bone morphogenetic protein 4 (BMP4) is a potent inhibitor of breast cancer metastasis." (PMID 38689334, 2024). "Additionally, inhibiting BMP4 gene expression can reduce anoikis resistance in breast cancer cells, offering a new perspective for preventing breast cancer invasion and metastasis." (PMID 39596658, 2024).
breast carcinoma (continued). "Gene signature upregulated by BMP4 in the absence of SMAD4 was associated with poor prognosis in breast cancer patients, whereas gene signature upregulated by BMP4 in the presence of SMAD4 was associated with improved prognosis." (PMID 38689334, 2024). "Interestingly, at the cytokine level, our results identified elevated BMP4 signaling in these three and other breast cancer cell lines, which was previously reported as a therapeutic target in the ER-positive breast cancer." (PMID 37669926, 2023). "Elevated expressions of GDF15 and BMP4 were associated with poorer prognosis comparing the low expression cohort (122.64 months) in HER2 negative patients with HER2 positive group (P<0.01), which indicates that GDF15 and BMP4 tend to promote the progression of breast cancer in HER2 (+) patients." (PMID 37333824, 2023). "Thus, a growing body of evidence suggests that BMP4 exerts its effects on breast cancer cells in two opposite directions—acting as a suppressor of primary tumor growth and simultaneously promoting cancer cell migration and invasion." (PMID 35694408, 2022). "Also, the discussed studies corroborated the metastatic/invasive suppressor role of BMP4 and defined BMP4 as a favourable prognostic marker in breast cancer patients." (PMID 36510219, 2022). "Similarly, a preclinical in vivo animal study showed the ability of BMP4 in preventing breast cancer spontaneous metastases." (PMID 36510219, 2022). "Low Bmp4 gene expression was also found in highly aggressive metastatic murine mammary tumours." (PMID 36510219, 2022). "We first analyzed BMP4 mRNA expression levels across different breast cancer molecular subtypes." (PMID 33649296, 2021). "Interestingly, BMP4 also promoted differentiation of normal mammary epithelial cells, highlighting BMP4 as a potent pro-differentiation factor in both normal and breast cancer cells." (PMID 33649296, 2021). "Next, following the increase in EMT, we examined whether BMP-4 is able to enhance the stem cell properties of the human breast cancer cell line MDA-MB-231, as well as it did in MCF-10A cells." (PMID 31409851, 2019). "It is also well known that BMP-4 is required for EMT in breast cancer cells." (PMID 31409851, 2019). "In addition, the BMP-4-dependent activation of Notch was demonstrated to enhance cancer stem cell properties in the breast cancer cell line MDA-MB-231." (PMID 31409851, 2019). "Interestingly, our finding contradicted some previous reports that showed that BMP4 inhibited proliferation of some cell types, including pancreatic α cells 26, pulmonary artery smooth muscle cells 27, and breast cancer cells." (PMID 30972973, 2019). "For other non-seed genes in breast cancer risk modules, a transcriptomic signature of BMP4 signaling exhibited by primary ER+ breast tumor patients was predictive of improved disease outcome or an improved biologic response to the treatment." (PMID 31860871, 2019). "Both Notch signaling and BMP-4-mediated signaling play important roles in breast cancer." (PMID 31409851, 2019). "We have provided an insight into the effects of BPA and B(a)P on the response of SCs to BMP2 and BMP4, which could contribute to very early stages of breast cancer initiation." (PMID 27740625, 2017). "The key may be that BMPs have bidirectional actions in breast cancer, such as BMP-4, which not only suppresses breast cancer cell growth, but also promotes invasion and migration." (PMID 28733469, 2017). "This study demonstrates that the differential responses to BMP4, reduced proliferation and induced migration, seen in breast cancer cell lines in vitro, are reflected in the expression pattern of BMP4 target genes, thus allowing us to uncover regulatory mechanisms associated with these phenotypes." (PMID 28077088, 2017).
breast carcinoma (continued). "To characterize the transcriptional mediators of these phenotypes, we performed RNA-seq and DNase-seq analyses after BMP4 treatment in MDA-MB-231 and T-47D breast cancer cells that respond to BMP4 with enhanced migration and decreased cell growth, respectively." (PMID 28077088, 2017). "Recent findings have revealed that BMP4 is overexpressed in breast cancer and may promote cell invasion and migration by modulating TGF-β factor signaling." (PMID 28947976, 2017). "Interestingly, BMP-4 inhibits aggressiveness in different breast cancer cell lines under different experimental conditions." (PMID 28733469, 2017). "In breast cancer Hs578T cells, BMP4 slightly downregulated asporin and phosphorylation of focal adhesion kinase (FAK) at tyrosine 397 (2.4 and 2.1 mean fold downregulation, respectively), while BMP2 did not cause any consistent changes (1.2 mean fold downregulation)." (PMID 27409832, 2016). "Next we examined the effects of BMP4 in 3D cultures of four breast cancer cell lines." (PMID 24053318, 2013). "In another study, BMP4 also showed the two sides of oncogenes and anti-oncogenes in breast cancer." (PMID 24099560, 2013). "We have previously shown, using a large set of breast cancer cell lines, that BMP4 treatment systematically inhibits proliferation in all cell lines and simultaneously increases migration of MDA-MB-231, MDA-MB-361 and HCC1954 cells, but reduces migrativeness of T-47D cells." (PMID 24053318, 2013). "To this end, we selected breast cancer cell lines with low endogenous expression of BMP4 (HCC1419, SK-BR-3), BMP7 (MDA-MB-231, T-47D) or both (HCC1954, MDA-MB-361, ZR-75-30) and treated them with the corresponding BMP ligand (rhBMP4 or rhBMP7) and vehicle controls." (PMID 22118688, 2011). "BMP4 and BMP7, in particular, have been implicated in breast cancer." (PMID 22118688, 2011). "Additionally, in vitro studies have implicated BMP4 and BMP7 as important regulators of proliferation and migration of breast cancer cells." (PMID 22118688, 2011). "The effects of exogenous BMP4 on breast cancer cell migration and invasion have also been studied." (PMID 22118688, 2011). "In addition several reports have shown a role of BMP-2 in invasion of lung, prostate, breast cancer cells and BMP-4 in ovarian cancer." (PMID 19366455, 2009). "For canonical, SMAD4-dependent BMP4 signalling, we generated a signature based on the most upregulated genes minus the most down-regulated genes that were also available in the Metabric dataset and assessed expression and prognostic value in breast cancer patients." (PMID 38689334, 2024). "To evaluate the clinical relevance of BMP4-induced canonical and non-canonical signalling pathways, we examined the expression levels and prognostic values of genes that are associated with these pathways in the Metabric breast cancer patient dataset." (PMID 38689334, 2024). "Indeed, therapeutic supplementation of recombinant BMP4 protein or restoring the expression of BMP4 sensitized the breast cancer cells to anoikis and significantly decreased the volume of circulating cancer cells with subsequent inhibition of metastatic niches to the bones and lungs." (PMID 36510219, 2022). "Interestingly, breast cancers are characterized by an increase in BMP4 and BMP7 ligands." (PMID 23840733, 2013). "In solid cancers, IL4 has been shown to be useful in colorectal cancer stem cell suppression, BMP4 was found to induce glioblastoma CSCs to differentiate into non-CSCs, and salinomycin, a selective potassium ionophore, could target breast cancer stem cell proliferation and induce differentiation." (PMID 21347385, 2011). "In breast cancer, FAM20C promotes bone metastasis by phosphorylating bone morphogenetic protein 4 and enhancing osteoclastogenesis." (PMID 41399371, 2026).
breast carcinoma (continued). "Specifically, in this study, we perform immunohistochemical and bioinformatic analyses to investigate the possible prognostic role of vimentin, SDF-1, BMP-2, BMP-4, PTX3, OPN, RANKL, and Runx2 on a large cohort of breast cancer patients." (PMID 39859358, 2025). "The bioinformatics analysis provided valuable insights into the possible prognostic and therapeutic significance of BMP-2, BMP-4, SDF-1, and vimentin in breast cancer." (PMID 39859358, 2025). "In patients with luminal A breast cancer, high expressions of BMP-4, SDF-1, and vimentin demonstrated a more substantial positive impact on overall survival (BMP-4 p = 0.0025; SDF-1 p = 0.0019; vimentin p = 0.00051)." (PMID 39859358, 2025). "Genes regulated by BMP4 and/or SMAD4 were assessed in a publicly available database of gene expression profiles of breast cancer patients." (PMID 38689334, 2024). "BCL2 expression can be enhanced by Bone Morphogenetic Protein 4 (BMP4), which promotes anoikis resistance in breast cancer cells." (PMID 39517115, 2024). "To confirm this unexpected observation of BMP4-induced suppression of metastasis even when SMAD4 levels are low, we utilized a second model, the human triple-negative MDA-MB-468 breast cancer line that lacks SMAD4 due to a homozygous deletion." (PMID 38689334, 2024). "BMP4 induces EMT in breast cancers via Notch signaling; it promotes invasion in breast cancer cells and colon cancer cells." (PMID 38256140, 2024). "BMP2, BMP4, GDF11 and TGFBR2 had relatively higher levels in bone metastases of breast cancer while BMP5, BMP7, BMPR2, BMPR1A and ACVR2A presented lower expression in the bone metastases, in the E-MTAB-4003 dataset." (PMID 37333824, 2023). "In four main subtypes of breast cancer, elevated expression of BMPR1B and ACVR2B were seen in Luminal A subtype, while BMP4, GDF15 and ACVR1B were higher in Luminal B, TGFBR1 and BMP8A were higher in HER2 positive, BMP2, BMP6 and GDF5 were higher in TNBC." (PMID 37333824, 2023). "Clinically, in silico data analysis revealed a favourable correlation between BMP4 high expression level and prolong overall survival (OS) and relapse-free survival (RFS) in breast cancer patients." (PMID 36510219, 2022). "BMP-4 enhances EMT and stem cell properties via the Smad-dependent pathway in both mammary epithelial and breast cancer cells, which is accompanied by the activation of Notch signaling." (PMID 35693928, 2022). "Another substrate, BMP4, is also involved in breast cancer bone metastasis, in which Fam20C facilitates the growth of human breast cancer MDA-BoM-1833 cells and its bone metastasis through phosphorylation of BMP4 to induce osteoclast differentiation." (PMID 34988120, 2021). "BMP-4 promotes CSC properties and epithelial mesenchymal transition by Notch signaling in breast cancer." (PMID 35004266, 2021). "BMP4 and FOXA1 have been reportedly involved in patients with relapse-free survival (RFS) and disease-free survival (DFS) in breast cancer." (PMID 32182819, 2020). "BMP8B was significantly active in primary breast cancer, while BMP2, BMP4, BMP5, BMP6, BMP8B were significantly active in liver metastasis." (PMID 31557971, 2019). "We therefore looked for co-expression of GREM1 and its preferred BMPs, BMP2, BMP4 or BMP7, in human breast cancer cell lines using Expression Atlas." (PMID 31694641, 2019). "Here, we examined the nature of BMP-4 signaling that mediates EMT in mammary epithelial cells and breast cancer cells." (PMID 31409851, 2019). "BMP-4 enhanced epithelial mesenchymal transition (EMT) and stem cell properties in both mammary epithelial cell line and breast carcinoma cell line." (PMID 31409851, 2019). "The expression levels of breast cancer stem cell markers, such as CD44 and Nanog33,43,44, as well as the expression levels of Jagged-1 and Hes1, were increased in BMP-4-treated MDA-MB-231 cells, compared to control cells." (PMID 31409851, 2019).
breast carcinoma (continued). "Together, these results strongly suggest that blocking CDK4 activity leads to increased expression of the differentiation factor BMP4, resulting in decreased CD44+/CD24− BCSC numbers, and further leading to inhibition of breast cancer stemness." (PMID 27759034, 2016). "Correspondingly, BMP-4 and BMP-9 were also found to be potential anticancer agents in breast cancer." (PMID 27661009, 2016). "Conversely, when present, CCN6 protein binds to BMP4 and inhibits the BMP4-mediated activation of MAP3K7/MAPK14 kinases and decreases the invasiveness of breast cancer cells." (PMID 26395334, 2015). "The list of these genes includes not only a large number of known breast cancer genes (e.g. CDH1, CDH3, BMP4, MTAP, CDKN2B), revealed by previous studies using breast tumor tissues and breast cancer cell lines but also novel genes." (PMID 24885402, 2014). "NDRG2 also suppresses matrix metalloproteinase-9 (MMP-9) expression through the induction of BMP-4 secretion and inhibits NF-kappaB activity and MMP-2 and -9 secretion, which abrogates the metastatic potential of breast cancer and fibrosarcoma cells." (PMID 25061501, 2014). "In PEG gel, BMP4 inhibited the growth of MCF-10A and the three breast cancer cell lines examined, thus closely resembling the 2D culture conditions, but in Matrigel, no growth inhibition was observed in MDA-MB-231 and MDA-MB-361 cells." (PMID 24053318, 2013). "The importance of BMP4 and BMP7 in breast cancer was highlighted in a survey of seven BMPs: these two ligands had the highest expression levels and were the most frequently expressed among 22 cell lines and 39 primary tumor samples." (PMID 22118688, 2011). "In order to obtain a general view of the cellular functions regulated as a result of BMP4 and BMP7 signaling in breast cancer cell lines, we performed a GO enrichment analysis on the data sets resulting from general filtering." (PMID 22118688, 2011). "The expression of BMP4 and BMP7 in breast cancer also has been demonstrated in several other reports." (PMID 22118688, 2011). "In this study, we have therefore set up an experimental procedure to identify potential BMP target genes in breast cancer by studying the effects of two BMP ligands, BMP4 and BMP7, on genome-wide gene expression." (PMID 22118688, 2011). "The present study was designed to gain knowledge in this topic, by exploring the effects of BMP4 and BMP7 signaling on gene transcription in seven breast cancer cell lines and throughout a 6-point time series, using a genome-wide approach." (PMID 22118688, 2011). "The aim of this study was to uncover the transcriptional responses of BMP4 and BMP7 signaling in breast cancer." (PMID 22118688, 2011). "All in all, we show that BMP4 and BMP7 have strong effects on gene expression in breast cancer cells, and that this transcriptional response and its functional outcome follow a temporal sequence." (PMID 22118688, 2011). "We explored the effects of BMP4 and BMP7 treatment on global gene transcription in seven breast cancer cell lines during a 6-point time series, using a whole-genome oligo microarray." (PMID 22118688, 2011). "One of the main goals of this study was to identify new BMP4 and BMP7 target genes relevant in breast cancer." (PMID 22118688, 2011). "The functional significance of BMP4 and BMP7 in breast cancer has been studied predominantly through the use of in vitro models." (PMID 22118688, 2011). "Our experimental approach allowed multiple types of analyses and revealed interesting insights into how the stimulation of BMP4 and BMP7 signaling influences the transcriptome of breast cancer cell lines." (PMID 22118688, 2011). "Several studies on the overexpression of BMPs, such as BMP-2, BMP-4, and BMP-7 in mammary tumor cells are suggestive of a role of BMPs in breast cancer development." (PMID 17997862, 2007).